RNU6-328P (RNA, U6 small nuclear 328, pseudogene)
Gene: Small nuclear RNA gene on chromosome 16 (7,004,007 to 7,004,112, reverse strand). Ensembl gene ENSG00000212189.
Homologues: Orthologues: chimpanzee U6 (94% identical), macaque U6 (90% identical), dog U6 (58% identical). Paralogues in human: RNU6-19P (84% identical), RNU6-536P (84% identical), RNU6-1152P (83% identical), RNU6-804P (82% identical), RNU6-1048P (81% identical), RNU6-1060P (81% identical), RNU6-1099P (81% identical), RNU6-12P (81% identical), RNU6-13P (81% identical), RNU6-16P (81% identical), RNU6-31P (81% identical), RNU6-32P (81% identical), and 1287 more.